CD80 (CD80 molecule)
Diseases named in the same sentence as CD80 in open-access papers (continued):
Sharing a sentence is not in itself a finding about the gene and the disease.
tumor (continued). "The changes to iMoDC surface phenotype are likely to be tumor-driven, as exposure to Met5A cells did not alter the percent of CD1a+, CD86+ or CD80+ iMoDCs, nor did it alter surface expression levels (MFIs) of CD86 or CD80 on iMoDCs, relative to DCs only." (PMID 25886502, 2015). "Since CD80 binds CTLA-4 after T cell activation, we hypothesized that the observed lack of persistence and poor anti-tumor efficiency of 19z1-CD80+ T cells could result from CTLA-4 inhibition." (PMID 26110267, 2015). "The 4T1 tumor cells did not further increase the maturation marker expression of mDCs, whereas the antigen-presenting molecules MHC-I and MHC-II and the co-stimulatory molecules CD80 and CD86 were markedly reduced on DCs stimulated by irradiated 4T1 cells." (PMID 27551446, 2015). "Importantly, the expression of MHC II, PD-L1 CD80 and Sca-1 was not significantly different on MDSC isolated from the tumor of non-modified CT26 cells when compared to CT26-GM-CSF tumors." (PMID 25869209, 2015). "EGFR inhibition did not change the expression of CD80, CD86, or PD-L1 on the tumor cells." (PMID 25240937, 2014). "We aimed to enhance the effect of tumor lysate with regard to induction of DC maturation, but as reported by others we had to face the problem that the tumor lysate rather did not induce DC maturation, in terms of upregulation of surface markers CD40, CD80, and CD86." (PMID 21615909, 2011). "Moreover, PRMT1 inhibition increased the CD80 MFI in macrophages, indicating a relatively higher level of CD80 activation and cytotoxic T cells (GranB+CD8+) in CT26-cGAS-WT, but not the CT26-cGAS-KO cell-engrafted tumor." (PMID 37193698, 2023). "Instead, non-classical co-stimulatory receptors beyond CD80/86 can be expressed by some cancer cells and are sufficient to activate certain T cell subsets, for example CD70, OX40-ligand, as well as molecules from adjacent, juxtaposed immune cells in the tumor microenvironment." (PMID 37508545, 2023). "In the draining lymph nodes (TdLNs) of an MC38 model, a radioimmunogenic tumor-bearing mouse model, RT did not change the number of tumor-migratory cDCs but promoted the maturation of DCs by upregulating the expression of the costimulatory molecules CD40 and CD80." (PMID 37208386, 2023). "The results showed no detectable expression of CD80, CD83, or CD86 on the surface of γδ T cells from PBMCs of normal donors (control), peripheral-derived γδ T cells, and γδ T cells directly isolated from tumor tissues (defined as tumor tissue-derived γδ T cells)." (PMID 24741609, 2014). "Most tumour cells are poor APC because of the low or absent expression of costimulatory molecules, but enforced expression of some of these (e.g. CD80, B7H2 or 4-1BBL) by gene transfer has resulted in enhanced antitumour responses and tumour rejection in different animal models." (PMID 12771917, 2003). "Furthermore, when DCs were incubated with culture medium supernatant of tumor cells, the percentage of CD80+ cells also increased by supernatant from Smad4KO but not WT PDAC cells, nor Smad4&StingKO cells, indicating the essential role of tumor‐intrinsic STING‐mediated signaling in DC activation." (PMID 35064757, 2022). "Notably, the expression levels of CD80 and CD40 on pDCs in tumor sites decreased in the shRNA-treated group, whereas the activation of pDCs in spleen was not impaired, suggesting that shRNA-induced tumor apoptosis might suppress the activation of pDCs." (PMID 31849942, 2019).
cancer (338 papers, 2003 to 2026). A tumor composed of atypical neoplastic, often pleomorphic cells that invade other tissues. "Classical M1 polarization is characterized by the upregulation of CD80 and iNOS genes, which are associated with the tumoricidal function of TAMs responsible for cancer cell engulfment and T cell recruitment." (PMID 40216772, 2025). "CD80 expression on myeloid cells has been associated with a pro-inflammatory phenotype and improved patient survival in certain cancers." (PMID 39702544, 2024). "It was found that the levels of PD-1/CD80+ sEVs, derived mainly from immunocytes, simultaneously increase in cancer patients’ circulation and are closely associated with the poor response to immunotherapy." (PMID 38719909, 2024). "Impressively, co-incubation of BMDCs with 4T1 cancer cells pretreated by “M1-MPNPs + L” caused obviously increased expression of CD80 and CD86, suggesting strong DC maturation." (PMID 37626073, 2023). "This is likely because patients with high CD80 expression efficiently clear mutated cells; thus any cancer that survives in such individuals must have a low TMB or else be eliminated by the immune system." (PMID 36892747, 2023). "Immunosuppression is mediated by cancer cells expressing programmed death-ligand 1 (PD-L1) and CD80 that bind PD-1 and cytotoxic T-lymphocyte-associated protein 4 (CTLA4) on cytotoxic T cells to suppress T cell activation." (PMID 33406733, 2021). "We identified four SNPs located in CD80 loci that were associated with sCD80 level as well as cancer outcomes." (PMID 32909077, 2021). "On the other hand, downregulation/loss of CD80 in cancer cells seem to occur mainly through epigenetic mechanisms." (PMID 31072360, 2019). "Conditioned media from GRP78-silenced cancer cells caused reciprocal regulation of CD80 and CD206, suggesting control of plasticity by secreted factors." (PMID 29113324, 2017). "A transient, low dose DAC exposure to EL4 cells in vitro and in vivo induces CD80 expression on cancer cells, which is likely the major cause of the induction of CTL response." (PMID 23671644, 2013). "Consistent with a pivotal role for CD80 in cancer immune surveillance, blocking CD80 signaling caused a significant increase in HGD frequency and extension (p = 0.01 and p = 0.04, respectively), whereas the number and total area of HGD foci were minimal in anti-CTLA4-treated mice." (PMID 25595911, 2015). "CD47 is a surface receptor on cancer cell and delivers the “don’t eat me” signal by interacting with SIRPα on myeloid cells, while costimulatory molecules CD80 and CD86 participate in the regulation of antigen presentation and T cell activation." (PMID 40708945, 2025). "And the finding demonstrated a strong correlation between elevated levels of immune checkpoints and the SREBF1 in ACC, notably KIR2DL3, IL2RA, CD80, IFNG, BTN3A2, and IL1A, also IFNA1 wass significantly associated with SREBF1 in the majority of cancers." (PMID 40668814, 2025). "As in the murine models, cancer cells lack costimulation markers, and CD80 and CD86 expression is limited to myeloid populations in the tumors." (PMID 41417245, 2025). "Numerous chemotherapeutic drugs and irradiation have been reported to modulate ROS levels in cancer cells and upregulate immune checkpoints like CD80, corroborating our current findings." (PMID 40746567, 2025). "We found that at baseline the cancer cells in vivo consistently lack CD80 and CD86, but can express PDL1, as anticipated." (PMID 41417245, 2025). "HPV-positive CC tumors exhibited epithelial cells with significant enrichment of immune checkpoint ligands (LGALS9, CD274, and TNFRSF14), whereas HPV-negative carcinomas predominantly activated the CD80/86-CTLA4 pathway." (PMID 41035636, 2025). "- CD80 increased with age in normal and cancer tissues. - CD80 expression differences are a consequence of immunosenescence rather than being influenced by disease or a response to treatment." (PMID 38590525, 2024).
cancer (continued). "Impressively, the co-incubation of BMDCs with 4T1 cancer cells pretreated with “BC@Z-M + L” markedly increased the expression of maturation markers CD80 and CD86, indicating strong DCs maturation." (PMID 39613774, 2024). "Evidence supports that ICAM1 binds to MUC1, which is known to be overexpressed in cancer cells and cancer stem cells, and CD80 binds to CTLA4, which is an immunosuppressive marker that is also expressed in cancer stem cells." (PMID 38903193, 2024). "During the induction phase of the anti-cancer immune response, immune checkpoint molecules inhibit the activation of effector T cells by interfering with the interaction between CD80/CD86 and CD28." (PMID 39507618, 2024). "The results indicated that T cells are the main source of increased PD-1/CD80+ sEVs levels upon the occurrence and development of cancers." (PMID 38719909, 2024). "Not only that, our results also reveal a positive correlation between LAPTM4A and multiple immune checkpoint (ICP) gene expressions, including the well-known CD274, PDCD1, and CD80, which tend to suppress effector T cells to promote cancer development." (PMID 38613802, 2024). "According to the literature, CTLA4 with a higher binding affinity to CD80 delivers inhibitory signals for activation of T lymphocytes and immune responses against malignant tumors." (PMID 39081321, 2024). "Targeting CD80, or triggering natural killer cell-mediated killing of cancer cells by inducing CD80 expression, has been explored as a possible cancer immunotherapy." (PMID 39575257, 2024). "In response to these cGAS-STING pathway-mediated cytokines, cancer cell fragments/particle-internalized immature DCs differentiate into mature DCs that express CD80 and CD86, as well as robust MHC class II, and exert cross-presentation activity." (PMID 38474078, 2024). "PD-L1, also known as B7-H1 or CD274, contributes to the inhibition of the cancer-immunity cycle by binding to negative regulators of T-cell activation such as PD-1 and B7.1 (CD80)." (PMID 38638433, 2024). "Our data expand on the causes of T-cell suppression as we have further identified an increase in immunosuppressive markers expressed on KEAP1-mutant cancer cells that inhibit the T-cell response (PD-L1, CD80/CD86, and CD155)." (PMID 38542481, 2024). "For a better understanding of the fundamental functions, we then investigated the potential cell sources of PD-1/CD80+ sEVs in cancer patients." (PMID 38719909, 2024). "Flow cytometry analysis indicated that PD-L1 and CD112 were the most expressed IC ligands by full epithelial and EpCAMhigh cancer cells, followed by CD80, Gal9, and CD155." (PMID 38914547, 2024). "These important findings regarding the potential harmful effects of PD-1/CD80+ sEVs on antitumour immunity serves as a warning signal for the improbability of using biogenic or synthesised vesicles carrying PD-1/CD80 for cancer treatment." (PMID 38719909, 2024). "CD80 was highly expressed in many malignant tumors, whereas in several others, including in LUAD, it was expressed at lower levels than in normal tissues." (PMID 36892747, 2023). "Nanoparticles were coated with cell membrane originating from genetically engineered CD80‐expressing cancer cells." (PMID 37933383, 2023). "In the cancer setting, comparable levels of antigen loading were observed in the lung and the medLN, but while cDC upregulated CD80 and CD86 in response to both BrightFlu antigen uptake, only CD86 was upregulated in the cancer setting." (PMID 37478193, 2023). "Atezolizumab is an engineered humanized monoclonal anti-PD-L1 antibody that inhibits the binding of PD-L1 to PD-1 and B7.1 (also known as CD80), thereby restoring anti-cancer immunity." (PMID 37727216, 2023). "Immunotherapy using antibodies to target immune checkpoints (immune checkpoint inhibitors, ICIs), including the PD-1/PD-L1 and CTLA-4/CD80 pathways, has shown promising anti-cancer effects in a variety of cancers." (PMID 37234171, 2023).
cancer (continued). "PD-L1 performs a functional role in regulating the cancer immune clearance cycle by binding to T cell-activated negative regulators, such as programmed cell death-1 (PD-1) and B7.1 (CD80)." (PMID 36090998, 2022). "CD80 is expressed on activated B cells, macrophages, DCs, and cancer cells and binds to CD28 on T cells." (PMID 36387279, 2022). "Current efforts to improve the efficacy of cancer immunotherapy are mainly focused on reversing T cell exhaustion by exploiting pathways such as the PD-L1/PD-1 signaling pathway and the CD80/-86/CTLA4 pathway." (PMID 35972800, 2022). "PD-L1 protein was spatially clustered with CD80 and ICOS proteins, markers of activated T cells, and both were strongly associated with genes involved in cancer progression, immunosuppression, and chemoresistance such as CDYL25 and TBKBP126." (PMID 36575294, 2022). "PD-L1, also known as B7-H1 or CD274, plays a part in inhibiting cancer-immunity cycle through binding to negative regulators of T-cell activation such as PD-1 and B7.1 (CD80)." (PMID 35621637, 2022). "Cancer cells can express regulatory ligands such as PD-L1, CD80/CD86, or Galectin-9 to provide a negative regulatory signal to T lymphocytes expressing their respective receptors PD-1, CTLA-4, and TIM-3, resulting in T cell exhaustion." (PMID 35159351, 2022). "Inonotus obliquus blocks CTLA-4/CD80 interaction and increases T cell activity so that cancer cells cannot escape the immune response." (PMID 36142412, 2022). "Anti-PD-L1 antibody relieves T cell suppression by inhibiting the binding of PD-L1 to programmed cell death protein 1 (PD-1) and B7.1 (also known as CD80), which are receptors on effector T cells, and exerts antitumor effects in various types of cancer." (PMID 34958105, 2022). "produced a nanoparticle with cell membrane derived from cancer cells engineered to express CD80, a costimulatory signal." (PMID 35715953, 2022). "Significantly higher median serum levels of BTLA, CD27 and CD80 proteins were found in the group of high-grade carcinomas compared to the group of low-grade carcinomas (p = 0.01, p = 0.01, p = 0.03, respectively)." (PMID 35204342, 2022). "In the mock-irradiated cancer microenvironment, there was a significant correlation between CD80 and Flt-1 (r = 0.7857, p = 0.04), and an inverse correlation between CD80 and IL-27 (r = −0.8214, p = 0.03)." (PMID 33540635, 2021). "CTLA-4 upregulation and binding with CD80/CD86 promotes T cell anergy, and cancer cells and TAMs have been shown to express CD80 and CD86." (PMID 34803925, 2021). "PD-L1, which is expressed on many cancer and immune cells, plays an important part in blocking cancer immunity by binding PD-1 and B7.1 (CD80), both of which are negative regulators of T-lymphocyte activation." (PMID 34018387, 2021). "The clinical translation of these findings will require an improved understanding of cancer cell CD80 expression in human malignancies." (PMID 31959281, 2020). "The role of NK cells in the remarkable response of CT26 to CTLA4 blockade as well as the potential mechanism of NK activation through CD80 expressed on CT26 cancer cells remains to be elucidated by future experiments." (PMID 31898484, 2020). "Collectively, these results suggest that CD80-expressing cancer cells are present in some solid epithelial cancers and some blood cancers, supporting the potential to select patients based on cancer cell CD80 expression for treatment with a FAK inhibitor." (PMID 31959281, 2020). "Together, these results indicate that the T cell engager and activator CD80-Fc, significantly boosts the antigen-specific T cell immune response to a diverse range of cancer-antigen targets." (PMID 32161596, 2020).
cancer (continued). "PD-L1 which is expressed on many cancer and immune cells, plays an important role in blocking the ‘cancer immunity cycle’ by binding to PD-1 and B7.1 (CD80), both negatively regulate T-lymphocyte activation." (PMID 32398042, 2020). "Together, the results of our study highlight the adjuvanting effect of T cell engagement either directly, CD80-Fc, or indirectly, Flt3L-Fc, for cancer vaccines." (PMID 32161596, 2020). "In particular, CD80 and HLA-DR were very low in healthy subjects and showed a trend of increased expression in cancer patients, especially after chemotherapy, with different degree in the three cell populations." (PMID 31973714, 2020). "Here, we show that expression of the T-cell co-stimulatory ligand CD80 on the surface of murine cancer cells sensitizes tumors to the highly selective and potent FAK kinase inhibitor BI 853520." (PMID 31959281, 2020). "It is well known that the costimulatory protein CD40 and CD80 molecules, which bind to helper T cell ligands, are generally expressed on B cells, macrophages, and dendritic cells, but only rarely expressed on cancer cells." (PMID 32325684, 2020). "A recent study demonstrated that cancer cells expressing CD80, a T cell costimulatory ligand, were more sensitive to pharmacological FAK inhibition and clearance by CD8+ cytotoxic T cells than cancer cells without CD80 expression." (PMID 32514188, 2020). "We further analyzed CD80-Fc with a variety of cancer vaccines and show that it universally led to an increased antigen-specific T cell response." (PMID 32161596, 2020). "Our findings provide rationale supporting the clinical development of FAK inhibitors in combination with patient selection based on cancer cell CD80 expression, and alternatively with therapies targeting T-cell co-stimulatory pathways." (PMID 31959281, 2020). "To further investigate the relationship between CD80 expression on cancer cells and sensitivity of tumors to the BI 853520 FAK inhibitor, we next expressed CD80 into the BI 853520-resistant SCC6.2 cell line." (PMID 31959281, 2020). "Antigen presentation and dendritic cell function are more active in CT26 compared to other models, and CD80 was expressed on CT26 cancer cells." (PMID 31898484, 2020). "Our data provide a mechanistic justification supporting an alternative strategy for patient stratification based on cancer cell CD80 expression." (PMID 31959281, 2020). "Immunosuppressive activity of certain cancer cells is gained by expression of CD80 and CD86.102,103 CTLA-4 and CD28 (co-receptor of TCR) recognize the same ligands." (PMID 32555170, 2020). "The results showed that the DPI-pretreated cancer cells stimulated monocyte polarization toward the phenotypes of F4/80 (high) M0 and CD80 (high) M1 macrophages." (PMID 32059469, 2020). "While cancer cells expressing CD80, the receptor for the T cell inhibitory protein CTLA4, showed remarkable sensitivity to FAK inhibitors, cancer cells with low levels of CD80 were resistant to FAK inhibition." (PMID 32514188, 2020). "Another immune checkpoint is mediated by binding of the ligands B7-1/2 (CD80, CD86) on activated antigen-presenting cells or cancer cells to cytotoxic T-lymphocyte-associated protein 4 (CTLA-4) on T cells, which also suppresses T-cell activity." (PMID 32455628, 2020). "Collectively, these findings suggest that cancer cell expression of CD80, most likely in combination with MHC-I expression, has the potential to identify tumors with increased sensitivity to FAK kinase inhibition." (PMID 31959281, 2020).